WNK1 (WNK lysine deficient protein kinase 1)
Diseases named in the same sentence as WNK1 in open-access papers (continued):
Sharing a sentence is not in itself a finding about the gene and the disease.
Hypertension (continued). "In humans, gain-of-function mutations in WNK1 and WNK4 result in Familial Hyperkalemia and Hypertension (FHHt; sometimes referred to as pseudohypoaldosteronism type II (PHAII) or Gordon Syndrome), a monogenic form of secondary hypertension characterized by hypertension and hyperkalemia." (PMID 35895103, 2022). "Gene mutations in WNK1 and WNK4 result in over-activation of the WNK-SPAK/OSR1 pathway, therefore increased phosphorylation and activation of NCC occurs in the kidney, resulting in hypertension." (PMID 33066544, 2020). "We also found that WNK4 (its mutations lead to hypertension) expression, but not WNK1, was significantly increased in CLDN7−/− CD cell lines as well as in primary CLDN7−/− CD cells, suggesting that the expression of WNK4 was modulated by CLDN7." (PMID 31382627, 2019). "Similarly, the AA genotype at the rs1468326 locus (WNK1) was twice as frequent in HYP versus NT (5.5% vs 2.3%, P < 0.0001), and associated with an increased adjusted OR of hypertension (4.1; 1.5–11.7) and a higher systolic BP (139.8 vs 130.1 mm Hg, P = 0.003)." (PMID 27082544, 2016). "Although these features are also thought to be caused by WNK1 or WNK4 mutations, the details of how these pathologies occur are unknown except for hypertension." (PMID 23383144, 2013). "Thus, patients with heterozygous CUL3 pathogenic variants are more likely to develop severe hyperkalemia, metabolic acidosis, hypertension, and growth impairment at an early stage than individuals carrying recessive KLHL3, dominant KLHL3, WNK4, or WNK1 pathogenic variants." (PMID 37895227, 2023). "Mutation in WNK1 and WNK4 genes could cause disturbances in the homeostasis of K+, salts, and pH level, whereas a mutation in AGT genes present on chromosome 1 results in an imbalance of angiotensinogen production, ultimately leading to hypertension." (PMID 30875817, 2019). "Seven hundred seventy-nine Caucasian hypertensive patients (HYP) recruited in 6 academic centers from Belgium, and 906 normotensive (NT) controls were genotyped for 5 single nucleotide polymorphisms—rs3754777, rs6749447, rs35929607 (STK39), rs1468326, and rs765250 (WNK1)—using the Snapshot method." (PMID 27082544, 2016). "Several genes including WNK1, WNK4, Bp1, Bp2, AGT, and ACE were reported to be involved in hypertension." (PMID 30875817, 2019). "These novel genetic data correlate well with what is known about WNK1 function, especially in relation to the primary phenotypes that characterise PHA2 - hyperkalemia and hypertension." (PMID 19347040, 2009). "The contribution of an impaired sympathoinhibitory ARN reflex to sex- and age-dependent hypertension in an NCC-dependent manner, via an impaired WNK1/WNK4 dynamic, suggests this pathway as a mechanism-based target for the treatment of age-dependent hypertension." (PMID 38976131, 2024). "The lysine kinases 1 and 4 (WNK1 and WNK4), identified as hyperactive in the hereditary disease pseudohypoaldosteronism type 2, are responsible for activation of NCC and consequent hypokalemia and hypertension." (PMID 36790288, 2023). "Based on the phenotype of familial hyperkalemia and hypertension (FHHt), and a report that WNK1 could stimulate SGK1 and ENaC, we next generated and characterized WNK1−/− mpkCCD cells, also using the CRISPR/Cas9 system." (PMID 36373794, 2022). "During the challenge of hypertension, the activated LRRC8A channel‐mediated‐Cl− efflux increases WNK1 phosphorylation, which in turn triggers AKT phosphorylation and promotes BASMCs proliferation, eventually exacerbates hypertension‐induced cerebrovascular vascular remodeling." (PMID 34725866, 2021). "Unlike the ADRB2, PRKCA and WNK1 genes, there was no reference found in the literature that connects the YEATS4 gene with pathways associated with hypertension or drug response." (PMID 33316892, 2020).
Hypertension (continued). "Mutations in WNK1 (With No K-lysine kinase 1, MIM 605232), cause Pseudohypoaldosteronism type 2 (PHA2, MIM 145260) – a rare autosomal dominant disorder primarily characterised by early onset hypertension and hyperkalemia." (PMID 19347040, 2009). "Interestingly, WNK1 signaling regulates renal epithelial transport, ion and cell volume homeostasis, and γ-aminobutyric acid (GABA) signaling—processes that are relevant for various pathologic conditions such as hypertension, cerebral edema, and neuropathic pain." (PMID 32325885, 2020). "Collectively, this work shows that the WNK1 pathway has a critical function in suppressing NLRP3 activation and suggests that pharmacological inhibition of this pathway to treat hypertension might have negative clinical implications." (PMID 34315884, 2021).
pseudohypoaldosteronism type 2 (29 papers, 2009 to 2025). A rare inherited form of hypertension characterized by hyperkalemia, hyperchloremic metabolic acidosis, normal or elevated aldosterone, low renin, and normal renal function. "Gain-of-function mutations in genes encoding for WNK1 or WNK4 cause Familial Hyperkalemic Hypertension (FHHt), also known as pseudohypoaldosteronism type 2 or Gordon’s syndrome." (PMID 32659887, 2020). "Large deletions in the first intron of WNK1 leads to an elevation in WNK1 expression causing an autosomal dominant disease called pseudohypoaldosteronism type II (PHA II; OMIM #145260) or Gordon's syndrome." (PMID 23451271, 2013). "Mutations in the WNK1 gene, encoding a serine-threonine kinase of the WNK (With No lysine (K)) family, have been implicated in two rare human diseases, Familial Hyperkalemic Hypertension (FHHt) and Hereditary Sensory and Autonomic Neuropathy type 2 (HSAN2)." (PMID 22701532, 2012). "Pseudohypoaldosteronism type 2 (PHA2), also known as Gordon syndrome, is a rare genetic disorder associated with variants in WNK1, WNK4, KLHL3, and CUL3." (PMID 39527282, 2025). "Mutations in the genes encoding WNK1 and WNK4, among others, are cause of a tubulopathy called familial hyperkalemic hypertension (FHHt) (also known as pseudohypoaldosteronism type II or Gordon syndrome)." (PMID 40668923, 2025). "WNK1 and WNK4 are known to be responsible genes of pseudohypoaldosteronism type 2 (PHA2) that is caused by large deletions in intron 1 of WNK1 or gain-of function mutations in WNK4." (PMID 36009402, 2022). "Mutations in WNK1 and WNK4 are associated with familial hyperkaliaemic hypertension (FHHt) or pseudohypoaldosteronism type II (PHAII) (OMIM: 145260) as a result of increased NCC activity." (PMID 32603001, 2021). "Pseudohypoaldosteronism type II (PHAII), also called Gordon syndrome, is a rare hereditary disease caused by variants in the WNK1, WNK4, KLHL3 and CUL3 genes." (PMID 34022862, 2021). "The first evidence linking WNK kinases to the CCCs was the discovery of mutations in the genes WNK1 and WNK4 in Familial Hyperkalemic Hypertension (FHHt), also known as Pseudohypoaldosteronism type 2 (PHAII), or Gordon syndrome." (PMID 33192599, 2020). "Pseudohypoaldosteronism type II (PHAII), characterized by hypertension, hyperkalemia, and metabolic acidosis, results from mutations in WNK kinase family members WNK1 and WNK4." (PMID 32714200, 2020). "Genetics and pathophysiology: Pseudohypoaldosteronism type II (PHAII), also referred to as Gordon syndrome, is autosomal dominant and affects the WNK serine-threonine kinase family (WNK1 and WNK4)." (PMID 31312622, 2019).
Hyperkalemia (18 papers, 2009 to 2025). An abnormally increased potassium concentration in the blood. "The patient exhibited persistent hyperkalemia, metabolic acidosis, and normotension, prompting genetic testing that identified a heterozygous mutation in the WNK1 gene." (PMID 40530196, 2025). "An example of this mechanism was that of a novel variant in the WNK1 gene, NM_018979.3:c.1903G > A, p.(Asp635Asn), which was identified in a patient with a family history of hyperkalaemia and a suspected clinical diagnosis of Gordon’s syndrome." (PMID 35869530, 2022). "Interestingly, it has been shown that a less severe form of GS featuring only hyperkalemia was caused by missense mutations in the WNK1 acidic domain." (PMID 37895227, 2023). "The inhibitory effect of hyperkalemia is mediated by WNK1/4 and aims to shift sodium downstream for stimulation of ENaC-mediated potassium secretion." (PMID 40220064, 2025). "WNK1+/FHHt mice display hyperkalemia, hypertension and metabolic acidosis as well as increased NCC abundance and phosphorylation." (PMID 29459793, 2018). "Moreover, hyperkalemia during Gordon’s syndrome (aka PHAII, FHHt) is rather consistent with renal K+ retention when WNK1 is over-active." (PMID 34204757, 2021).
glioma (15 papers, 2014 to 2025). A benign or malignant brain and spinal cord tumor that arises from glial cells (astrocytes, oligodendrocytes, ependymal cells). "In glioma cells, WNK1 associates with multiple ion transporters and contributes to migration by modulating volumetric changes." (PMID 31291965, 2019). "Pharmacological inhibition of NKCC1 significantly reduces glioma cell migration after TMZ treatment with drugs that inhibit elements of the WNK1/OSR1/NKCC1 signaling pathway." (PMID 40725030, 2025). "IHMT-337 targets EZH2 in vitro to inhibit WNK1 activation, thereby suppressing glioma cell migration." (PMID 38886655, 2024). "WNK1 is aberrantly expressed in non-small cell lung cancer, gliomas, renal tumors, breast cancer, and hematological tumors." (PMID 37980468, 2023). "WNK1 knockdown in primary glioma cells results in attenuated phosphorylation of NKCC1, the ubiquitously expressed ion co-transporter, in response to the chemotherapeutic drug temozolomide, reducing glioma cell migration." (PMID 35813203, 2022). "Small interfering RNA‐mediated WNK1 or OSR1 knockdown reduced glioma migration by eliminating NKCC1‐regulated phosphorylation activation." (PMID 37786890, 2022). "In this study, we further examined effects of chronic inhibition of NKCC1 activation via BMT or STS66 on WNK1-SPAK/OSR1-NKCC1 signaling pathway in glioma cells in response to TMZ." (PMID 32848856, 2020). "While robust expression of WNK1 kinase is also expressed in normal brain tissues and tumor tissues of all glioma grades." (PMID 24555568, 2014). "Small interfering RNA (siRNA)-mediated knockdown of WNK1 or OSR1 was used to explore their roles in regulation of NKCC1 activity in glioma cells." (PMID 24555568, 2014). "Taken together, these novel findings suggest that combination of TMZ-mediated chemotherapy with inhibition of the WNK1/OSR1/NKCC1 signaling pathway presents a new strategy for improving glioma treatment." (PMID 24555568, 2014). "Pharmacological inhibition of NKCC1 with its potent inhibitor BMT or siRNA knockdown of WNK1 or OSR1 significantly decreases glioma cell migration after TMZ treatment." (PMID 24555568, 2014). "In primary GBM cells and in mouse glioma, TMZ caused an increase in WNK1 phosphorylation." (PMID 41009329, 2025). "In addition, IHMT-337 targets EZH2 in vitro to inhibit WNK1 activation, thereby suppressing glioma migration." (PMID 38886655, 2024). "Taken together, these findings suggest that the WNK1/OSR1/NKCC1 signal pathway may be important in pathogenesis of glioma." (PMID 24555568, 2014). "Moreover, the WNK1/OSR1/NKCC1 signaling pathway plays an important role in glioma migration and is stimulated by TMZ." (PMID 24555568, 2014). "Reduce K+ and Cl− concentrations intracellularly, increase NKCC1, WNK1, and OSR1 phosphorylation, and enhance glioma migration." (PMID 37786890, 2022). "Taken together, these data suggest that blocking NKCC1 activity has impact on TMZ-induced activation of the WNK1-SPAK/OSR1-NKCC1 signaling pathway in both GL26 and SB28 glioma cells." (PMID 32848856, 2020). "The WNK1/SPAK/OSR1 signaling pathway is a well-studied upstream regulatory component of NKCC1, and it has been reported that WNK1 and OSR1 regulate the activation and phosphorylation of NKCC1 in human glioma cells." (PMID 29029515, 2017). "We report here that WNK1 and OSR1 are the dominant upstream regulatory kinases of NKCC1 in glioma cells." (PMID 24555568, 2014). "WNK1/OSR1 kinases function in stimulation of NKCC1 activity to maintain intracellular K+ and Cl- and cell volume homeostasis, which is important for glioma migration." (PMID 24555568, 2014). "First, we characterized expression of WNK1, SPAK, OSR1, and NKCC1 protein in human neural stem cells (NSC), human astrocytes (HA), primary glioma cells (GC#99 and GC#22), and GBM cell line U87." (PMID 24555568, 2014).
glioma (continued). "siRNA-mediated knockdown of WNK1 or OSR1 reduces intracellular K+ and Cl- content and RVI in glioma cells by abolishing NKCC1 regulatory phospho-activation." (PMID 24555568, 2014). "We show that compared to human neural stem cells and astrocytes, human glioma cells exhibit robust increases in the activation and phosphorylation of NKCC1 and its two upstream regulatory kinases, WNK1 and OSR1." (PMID 24555568, 2014). "In addition to WNK1, WNK3 can also maintain NKCC1-mediated transport thereby inducing regulatory volume increase (RVI) in glioma cells." (PMID 36123332, 2022). "TMZ treatment activates the WNK1/OSR1/NKCC1 pathway, thus increasing the glioma migration." (PMID 36292952, 2022). "We previously found that TMZ stimulated NKCC1 protein upregulation and activation in human primary glioma cells (GC#99 and GC#22) through With-No-K (lysine) kinase 1 (WNK1) and oxidative stress-responsive kinase 1 (OSR1) signaling pathway." (PMID 32848856, 2020). "Unexpectedly, TMZ activates the WNK1/OSR1/NKCC1 signaling pathway and enhances glioma migration." (PMID 24555568, 2014). "Together, our data show a novel role for the WNK1/OSR1/NKCC1 pathway in basal and TMZ-induced glioma migration, and suggest that glioma treatment with TMZ might be improved by drugs that inhibit elements of the WNK1/OSR1/NKCC1 signaling pathway." (PMID 24555568, 2014). "We speculate that WNK1/OSR1-mediated phosphorylation of NKCC1 protein may alter its interaction with ERM complex and promote glioma cell migration." (PMID 24555568, 2014). "The discrepancy of these findings on WNK1 and WNK3 expression may result from heterogeneity of the glioma cells." (PMID 24555568, 2014). "TMZ may activate the WNK1/OSR1/NKCC1 signaling pathway and enhance glioma cell migration." (PMID 40725030, 2025). "Expression of NKCC1 and its upstream kinases With-No-K (Lysine) kinase 1 (WNK1) and oxidative stress-responsive kinase-1 (OSR1) in different human glioma cell lines and glioma specimens were detected by western blotting and immunostaining." (PMID 24555568, 2014). "In the present study, we investigated whether WNK1-SPAK/OSR1 signaling pathway regulates NKCC1 activity in GCs and whether this signaling pathway is involved in regulation of glioma migration, with and without chemotherapeutic treatment." (PMID 24555568, 2014).
Gordon syndrome (14 papers, 2009 to 2023). An extremely rare multiple congenital malformation syndrome characterized by congenital contractures of hand and feet with variable degrees of severity of camptodactyly, clubfoot and, less frequently, cleft palate. "The patient showed heterozygosity for a variant in the WNK1 gene, which typically causes Gordon syndrome; however, our patient had a normal blood pressure." (PMID 35859812, 2022). "The phenotypic severity of Gordon syndrome varies according to different causative mutations (CUL3 > recessive KLHL3 > dominant KLHL3 > WNK4 > WNK1)." (PMID 31795491, 2019). "Intronic deletions in WNK1 gene cause Gordon’s Syndrome, an autosomal dominant, hypertensive and hyperkalemic disorder." (PMID 23285140, 2012). "In the second type of Gordon’s syndrome, a large intronic mutation causes an increase in WNK1 expression." (PMID 17647025, 2009). "Since the recognition of this predominantly autosomal dominant condition in the 1960s, the study of families with Gordon syndrome has revealed four genes WNK1, WNK4, KLHL3, and CUL3 to be implicated in its pathogenesis after a phenotype–genotype correlation was realised." (PMID 31795491, 2019). "In humans, WNK1, WNK4, CUL3, and/or KLHL3 mutations manifest as Gordon’s syndrome, a heritable form of hypertension associated with salt-sensitive hypertension, hyperkalemia, metabolic acidosis, and thiazide sensitivity." (PMID 36028759, 2022). "As mutant WNK1 increases WNK1 expression, ENaC and BK stimulation are exaggerated in Gordon syndrome." (PMID 31795491, 2019). "Inappropriate WNK1 activation during Gordon’s syndrome compromises this balance leading not only to inhibition of ROMK, but also to decreased BK-dependent K+ secretion due to excessive NaCl (i.e., volume) retention by the distal convoluted tubule thus causing little flow in the collecting duct." (PMID 34204757, 2021). "We next selected 15 different dominant Gordon's syndrome mutations located in different domainsof KLHL3, generated in stable HEK-293 cell lines,and tested how each mutation affects association with CUL3 and WNK1." (PMID 23387299, 2013). "Mutations in WNK1 and WNK4 cause familial hypertension, the Gordon syndrome." (PMID 21520334, 2011). "The KLHL3 interaction site in WNK1 is on a non-catalytic region, which is interestingly the equivalent site on WNK4, which encompasses mutated residues in Gordon syndrome patients." (PMID 31795491, 2019).